IL1B (interleukin 1 beta)
Diseases named in the same sentence as IL1B in open-access papers (continued):
Sharing a sentence is not in itself a finding about the gene and the disease.
hepatocellular carcinoma (continued). "Surprisingly, we found that upon either HCV exposure or infection neither immortalized primary human hepatocytes (PH5CH8 and IHH cells) nor hepatoma cells (Huh7) expressed inducible IL-1β mRNA or secreted appreciable levels of mature IL-1β." (PMID 23633957, 2013). "In hepatocellular carcinoma, the level of CXCL11 secreted by CAFs was considerably elevated compared with that of normal fibroblasts, and CXCL11 stimulated the upregulation of circUBAP2 expression, which further indirectly affected the levels of IL-17 and IL-1β by inhibiting miR-4756 expression." (PMID 40109856, 2025). "Moreover, recent reports demonstrated that IL-1β can activate the STAT1 pathway by negatively modulating ERK2 activation in the target cells and synergistically elevates PD-L1 expression through the coordination with IFNγ in hepatocellular carcinoma." (PMID 38166970, 2024). "MiR-132 also inhibits proliferation in hepatocellular carcinoma (HCC) by inactivating the AKT / mTOR signaling pathway, and by inhibiting IL1β and IL6 expression through inhibition of the transcriptional co-activator P300." (PMID 33539381, 2021). "IL-6 can promote hepatocellular carcinoma (HCC) growth and metastasis via antagonism of TNF-α and IL-1β immune response." (PMID 31867004, 2019). "Therefore, we did not detect any IL-1β secretion in HCV infected hepatoma cell lines." (PMID 24400125, 2014). "Moreover, in another hepatoma cell line Huh7.5.1 cells, 4 days after HCV infection, no IL-1β was detected either." (PMID 24400125, 2014).
pancreatic cancer (125 papers, 2000 to 2026). "Some studies indicated high IL1B expression was associated with poor prognosis in patients with pancreatic cancer." (PMID 40535567, 2025). "A recent study identified IL-1α and IL-1β released by pancreatic cancer cells and tumor-associated macrophages as relevant stimuli for TSLP release from CAFs." (PMID 40873585, 2025). "IL-1β was also found to mediate the association between obesity and pancreatic cancer as well as associate with tumor growth and carcinoma cell migration." (PMID 37781392, 2023). "Proinflammatory cytokine Il1β affects cell proliferation, differentiation, and apoptosis, and oxidative stress stimulates an excess release of Il1β, subsequently affecting pancreatic beta cells, which has been implicated in pancreatic cancer development." (PMID 37763073, 2023). "Adipocyte- and PSC-secreted IL-1β recruits tumour-associated neutrophils, activates PSCs and promotes pancreatic cancer progression and chemoresistance." (PMID 35986089, 2022). "IL-1β expression in a pancreatic tumor microenvironment is associated with treatment resistance and poor prognosis." (PMID 35741028, 2022). "NET-associated IL-1β was recently found responsible for the EMT process of pancreatic cancer via EGFR-ERK pathway." (PMID 34868992, 2021). "In other cancer types, such as pancreatic cancer, it has been shown that the possession of a certain genotype results in an increased IL-1b production, which was associated with shortened survival and increased serum CRP level." (PMID 30647842, 2018). "The present study examined the effect of a polymorphism of the interleukin (IL)-1b gene upon the inflammatory state and survival in pancreatic cancer." (PMID 11076651, 2000). "Furthermore, NET-associated IL-1β is involved in the epithelial-to-mesenchymal transition (EMT) process of pancreatic cancer by activating EGFR-ERK pathway." (PMID 34868992, 2021). "Furthermore, IL-1β can enhance the invasive capacity of pancreatic cancer cells, while free IL-18 levels are increased in the blood of pancreatic cancer patients and are associated with poor survival." (PMID 32974137, 2020). "Furthermore, high levels of IL-1β in tumors and serum were associated with higher tumor grades and increased invasion of breast, pancreatic cancer, and myelogenous leukemia, and were also associated with poor prognosis." (PMID 32556504, 2020). "Recently, it was reported that IL-1β gene promoter single nucleotide polymorphisms (IL-1β secretory phenotype) are associated with an increased risk for pancreatic cancer and that IL-1β participates in opioid-resistant pain, such as bone cancer and neuropathic pain." (PMID 20979661, 2010). "Ultimately curcumin treats pancreatic cancer by interfering with IL1B to inhibit inflammatory response through modulation of multiple signalling pathways." (PMID 40535567, 2025). "The expression of high levels of IL-1β was associated with lower overall survival and progression-free survival in patients with non-small cell lung cancer (NSCLC) and pancreatic cancer who were administered chemotherapy." (PMID 40244135, 2025). "Tumor cell-derived IL-1β promotes desmoplasia and immune suppression during pancreatic cancer progression." (PMID 41145465, 2025). "Public database analysis confirmed a significant increase in LCN2 mRNA levels in pancreatic cancer cells treated with IL-1β for 24 h compared with those in untreated controls." (PMID 41436606, 2025). "According to reports, TNFSF9 regulated macrophage M2 polarization through the Src/FAK/p-AKT/IL-1β signaling pathway, thereby facilitating the worsening of pancreatic cancer." (PMID 40830812, 2025).
pancreatic cancer (continued). "Research found that IL1B not only promoted proliferation and survival of pancreatic cancer but also enhanced tumor metastasis and invasion by influencing polarization of immune cells within tumor microenvironment." (PMID 40535567, 2025). "Consistently, loss or inhibition of PTEN, an enzyme responsible for the dephosphorylation and inactivation of Akt, increases NF-κB transcriptional activity and IL-1β production in pancreatic cancer cells." (PMID 39858071, 2025). "In our study, we demonstrate that TNF-α and IL-1β also reprogram the metabolic landscape of pancreatic cancer cells, rendering their reliance on the de novo pyrimidine synthesis pathway." (PMID 41243973, 2025). "Studies on pancreatic cancer have demonstrated that IL-1β secretion by macrophages within the tumor microenvironment can induce angiogenesis and consequently promote cancer progression." (PMID 39838454, 2025). "Recent reports showed that tumor cell–derived IL-1β induces immune suppression in the pancreatic cancer microenvironment." (PMID 40060615, 2025). "Other research also suggests that IL-1β secreted by pancreatic tumors induces the infiltration of various immunosuppressive cells." (PMID 38634049, 2024). "Interleukin-1β (IL1B) secreted from neutrophils was reported in pancreatic cancer and was found related to cancer cachexia by induing upregulated expression of LCN2 in the Lcn2-KO mouse model." (PMID 38769374, 2024). "Inflammatory cytokines like TNF-α, IL-1β and IL-6 were estimated in the spinal tissue of 5HT2A antagonist treated pancreatic cancer mice." (PMID 38629654, 2024). "The results showed a sustained increase in levels of the mRNA expression of TNFα, IL-1β, and IL-6 in hypothalamic microglia, which started from the pre-cachexia stage and lasted for the cachexia stage after pancreatic cancer cell transplantation." (PMID 38685046, 2024). "TA-MSCs can produce NO, which induces resistance to etoposide in pancreatic tumor cells and forms a positive feedback loop with IL-1β, contributing to chemotherapy resistance." (PMID 38835055, 2024). "As IL-1β is also highly expressed in PDAC tumour cells and other cancer-associated stromal cells in pancreatic cancer, it is possible that PDAC-derived IL-1β can directly induce the proliferation of neighbouring cancer stem cells, resulting in tumour growth." (PMID 39430099, 2024). "We have identified novel and important findings that IL-1b-mediated Regnase-1 downregulation induced MDSCs and promoted pancreatic cancer through the evasion of anticancer immunity." (PMID 37814340, 2023). "We subsequently showed that IL-1β-mediated Regnase-1 downregulation recruited MDSCs to tumor sites and promoted pancreatic cancer progression via mitigation of cytotoxic T lympohocytes-mediated antitumor immunity." (PMID 37814340, 2023). "IL1β blockage rewired the drug resistance of pancreatic tumors in vivo, and IL1β inhibitors are being actively examined in clinics (NCT04581343)." (PMID 36762766, 2023). "We also found that the inflammatory cytokine IL-1β negatively regulated Regnase-1 in pancreatic tumor cells." (PMID 37814340, 2023). "IL-1b-mediated Regnase-1 downregulation induces MDSCs and promotes pancreatic cancer through the evasion of anticancer immunity." (PMID 37814340, 2023). "For example, IL-1β produced from pancreatic cancer cells treated with LPS plus ATP increases cell proliferation, indicating pyroptosis in cancer cells to be a two-edged sword." (PMID 36932407, 2023). "Breast and pancreatic cancer cells can transform normal dermal fibroblasts into CAFs through the IL-1β/NFκB signaling cascade, thereby enhancing the inflammatory TME." (PMID 37821959, 2023). "IL-1β has been identified as an important cytokine in the development of pancreatitis and pancreatic cancer as well as in the progression from pancreatitis to pancreatic cancer." (PMID 37781392, 2023).
pancreatic cancer (continued). "From the progression of pancreatitis to pancreatic cancer, IL-1β was found to promote tumorigenesis partly via an expansion of immune-suppressive B lymphocytes." (PMID 37781392, 2023). "We reported that IL-1β cytokine derived from pancreatic cancer promoted the population of M2 macrophages, MDSCs, CD1dhiCD5+ regulatory B cells, and Th17 cells, resulting in immunoregulation." (PMID 37296628, 2023). "It is known that NLRP3 signaling drives resistance to anti-PD-1 immunotherapy and is responsible for adaptive immune suppression through promoting the production of IL-1β in pancreatic carcinoma." (PMID 36900234, 2023). "Neutralization of IL-1β attenuated the effects of IFI-16 overexpression in pancreatic cancer cells on TAM." (PMID 35739593, 2022). "According to a previous study, LPS-induced inflammation in the presence of ATP activates NLRP3, which enhances pancreatic cancer cell proliferation by boosting caspase-1 activity, resulting in total IL-1β production." (PMID 35677632, 2022). "Studies have shown that tumor cell-derived IL-1β promotes the proliferation of fibrous tissue and immunosuppression in pancreatic cancer." (PMID 36248807, 2022). "In pancreatic cancers, CAFs expressing IRAK4 can induce resistance to chemotherapy by IL1β secretion that activate the NFκB pathway in pancreatic cancer cells." (PMID 35681591, 2022). "IL-1β, IL-6, IL-8, IL-10, TGF, and VEGF are PDAC-associated cytokines studied in duplicate in more than four studies, and are elevated in pancreatic cancer." (PMID 35159120, 2022). "Our results showed that various inflammatory cytokines, such as IL-1β, IL-6, IL-8, and IL-15, were more expressed in pancreatic cancer than in the matching normal tissue." (PMID 35630552, 2022). "Activation of Src/FAK/p-Akt/IL-1β signaling by TNFSF9 is shown to increase pancreatic cancer metastasis by modulating the M2 polarization of macrophages." (PMID 36359832, 2022). "In preclinical models of pancreatic cancer, tumor cells express IL1β to establish an immunosuppressive tumor microenvironment that fosters tumor progression." (PMID 36561929, 2022). "In pancreatic cancer, IL-1β activated quiescent pancreatic stellate cells and promoted an immunosuppressive microenvironment rich in M2 macrophages, myeloid-derived suppressor cells, regulatory B cells, and Th17 cells." (PMID 35912252, 2022). "IL-1β is known to be related to inflammation responses, cancer progression, and cancer cell invasiveness in pancreatic cancer." (PMID 36140220, 2022). "Recent research found that tumour cell-derived IL-1β is essential for the establishment of pancreatic cancer desmoplasia." (PMID 35986089, 2022). "A study reported a significant decrease in the level of IL-1β in the plasma of a DMAPT-treated pancreatic cancer mouse model." (PMID 35096301, 2021). "The autocrine role of IL1β in inducing chemoresistance in pancreatic cancer cells was first demonstrated in 2002." (PMID 34066976, 2021). "And, the inhibition of the formation of NETs and the blockade of IL‐1β can effectively attenuate the EGFR‐induced progression of pancreatic cancer." (PMID 33955688, 2021). "Inhibition of inflammasome activation prevents infiltration of IL-1β that retards pancreatic cancer cell proliferation." (PMID 34150748, 2021). "Taken together, these data suggest that IL‐1β is responsible for NETs‐induced pancreatic cancer cell mobility and EMT." (PMID 33955688, 2021). "Taken together, NETs facilitated EMT, migration and invasion via IL‐1β/EGFR/ERK pathway in pancreatic cancer cells." (PMID 33955688, 2021). "The product of inflammasome activation, IL-1β, was significantly increased in pancreatic cancer tissue." (PMID 34150748, 2021). "IL-1β secretion from TAMs was reported to promote the epithelial-to-mesenchymal transition of pancreatic tumor cells and therefore contribute to its distant metastasis." (PMID 34150748, 2021).
pancreatic cancer (continued). "Pancreatic carcinoma cells were shown to overexpress mRNAs of various cytokines (IL-1β, IL-6, IL-10, IFNγ, TGF-β1, etc.)and IL-1β, TGF-β2, TGF-β3 proteins." (PMID 33806879, 2021). "We show in vitro that IL-1α and IL-1β released by pancreatic cancer cells and tumor cell-conditioned macrophages are crucial for TSLP secretion by CAFs." (PMID 30760333, 2019). "In pancreatic cancer, systemic levels of IL-1β and IL-6 showed a trend towards the development of future thrombosis." (PMID 31847343, 2019). "In pancreatic cancer, high expression levels of IL-6, a cytokine produced by a variety of cells including immune and pancreatic tumor cells, and IL-1β were correlated with poor overall and progression-free survival in pancreatic cancer patients." (PMID 31150430, 2019). "Results showed that P2X7R's key inflammasome components, IL-1β and caspase-1 are highly expressed (p < 0.05) in pancreatic tumors." (PMID 29228654, 2017). "Pancreatic tumor cells also release the pro-inflammatory cytokines IL-1β and TNF-α, which play a critical role in the malignancy of pancreatic ductal adenocarcinoma (PDA)." (PMID 29245934, 2017). "In the MIA PaCa2 pancreatic cancer cell line, IL-1β reduced adhesion to laminin while IL-1α increased fibronectin adhesion but impaired collagen I adhesion." (PMID 27556857, 2016). "Infection by H. pylori promotes upregulation of NF-κB, which is constitutively activated in several types of cancers, including pancreatic cancer, and can also be induced by several types of inflammatory cytokines including IL-1β in pancreatic cancer." (PMID 26347203, 2015). "For example, candidate gene studies have consistently found that polymorphisms in the IL-1β and MTHFR genes were associated with individual susceptibility to both intestinal-type gastric cancer and pancreatic cancer." (PMID 24495377, 2014). "In pancreatic cancer cells, IL-1β has been shown to mediate adhesion and invasion, as well as modulating chemoresistance by activating the NF- κB and ERK signaling pathways." (PMID 23704929, 2013). "Moreover, it was suggested that IL-8 and IL-1β are critical markers for the prognosis and drug resistance of pancreatic cancer." (PMID 41488204, 2026). "It was previously reported that IL-8 and IL-1β levels are elevated in pancreatic cancer patients." (PMID 41488204, 2026). "Another recent publication demonstrated the role of IL-1β+ TAMs in pancreatic cancer." (PMID 40427186, 2025). "A study revealed that an inflammatory interplay between IL-1β-expressing TAMs and pancreatic cancer cells drives disease progression and that targeting IL-1β activity could reprogram the immune microenvironment and control tumor growth." (PMID 40243455, 2025). "This inconsistency could be explained from the view of the relationship between IL-1β and pancreatic cancer, whose expression is increased in the carcinoma tissues compared to para-carcinoma tissue." (PMID 40604924, 2025). "Notably, while the NLRP3 inflammasome was found to be responsible for IL-1β processing in pancreatic cancer cells, its expression and activation are mostly detected in tumor-associated stromal or immune cells rather than cancer cells." (PMID 39858071, 2025). "IL-1α and IL-1β from pancreatic cancer cells released TSLP from CAFs." (PMID 40873585, 2025). "TLR4-induced secretion of IL-1β shaped the immunosuppressive microenvironment of pancreatic cancer." (PMID 37990304, 2023). "IL-1β has been associated with immune suppression and inhibition of CD8 + T cell activation in pancreatic cancer, but our study did not observe a significant prognostic association with IL-1β." (PMID 37127565, 2023). "Previous studies demonstrated that IL-1β is produced by pancreatic cancer stroma." (PMID 35986089, 2022). "In addition, high serum levels of IL-1β are a poor prognostic factor in pancreatic cancer patients receiving gemcitabine treatment." (PMID 36264639, 2022).